METTL3 (methyltransferase 3, N6-adenosine-methyltransferase complex catalytic subunit)
Diseases named in the same sentence as METTL3 in open-access papers (continued):
Sharing a sentence is not in itself a finding about the gene and the disease.
cancer (continued). "Here, we present the expression changes of m6A methyltransferases METTL3 and METTL14, as well as demethylases ALKBH5 and FTO, across seven of the most prevalent cancers worldwide according to the TCGA database." (PMID 40136363, 2025). "AREG mRNA is stabilized by m6A modification by METTL3, and the upregulation of AREG expression promotes cancer progression." (PMID 40448344, 2025). "Currently, multiple m6A writers, including METTL3, METTL14, WTAP, and VIRMA, have been shown to play critical roles in HIF-1 signaling, primarily in cancer progression." (PMID 40102715, 2025). "Recently, STC-15, an inhibitor of the m6A writer METTL3, has become the first RNA-modifying enzyme inhibitor to enter clinical trials (NCT05584111) for cancer treatment." (PMID 40102715, 2025). "In NPC, METTL3 stabilizes LINC00313, which recruits PTBP1, promoting STIM1 expression and enhancing cancer stemness." (PMID 39695216, 2024). "In certain circumstances, restoration of METTL3 and METTL14 expression to re‐establish m6A distribution can inhibit cancer cell progression." (PMID 39006762, 2024). "The multiple roles of METTL3 in driving and maintaining tumor growth make it a model candidate for PROTAC development with promising potential in future cancer therapies." (PMID 40453361, 2024). "Targeting m6A‐related enzymes, such as METTL3 and FTO, can effectively inhibit cancer cell growth and proliferation." (PMID 39445003, 2024). "METTL3, as a core component of the multifaceted m6A methyltransferase complex (MTC), has been reported to play critical roles in various cancer types." (PMID 38605400, 2024). "The most typical family members, METTL3 and METTL14, dimerize to form N6-methyl ladenosine (m6A) RNA methyltransferase, which has an established role in cancer progression." (PMID 38370374, 2024). "Furthermore, METTL3 inhibition may hold potential as a therapeutic strategy for other ALT+ cancers." (PMID 38180812, 2024). "Several cancer cell lines were treated with STM2457, an enzymatic inhibitor of RNA m6A methyltransferase METTL3, and explored the transcriptome changes with RNA sequencing (RNA‐seq)." (PMID 39568154, 2024). "Specific PROTACs induced significant degradation of METTL3 and METTL14 across multiple cancer cell lines, demonstrating a new approach to modulate epitranscriptomic proteins in cancer therapy." (PMID 39377984, 2024). "In cancer cells, we found that MUC1-C decreases expression of (i) RBM15/B, (ii) WTAP, and (iii) METTL3/14." (PMID 38740827, 2024). "Recent reports have shown that METTL3 and WTAP, two components of the functional methyltransferase complex, can influence cell proliferation in different cancer types through the AKT signaling pathway." (PMID 38649363, 2024). "Also, our findings underscore the significant METTL3 potential in regulating fundamental biological processes such as cell cycle, apoptosis, colony formation, and the acquisition of stemness characteristics in cancer cells, which profoundly impacts the efficiency of cisplatin treatment." (PMID 38966069, 2024). "Methyltransferase Like 3 (METTL3), installing m6A in RNAs, is highly expressed in NSCLC and promotes cancer progress." (PMID 38688909, 2024). "Altered METTL3 expression can affect the expression of DNA damage response (DDR)‐related genes and impair the repair of radiation‐induced DNA damage, rendering cancer cells more resistant to irradiation‐induced cytotoxicity." (PMID 39367700, 2024). "Regarding the exact mechanism by which METTL3 and its target SRPK1 promote LUAD progression, we considered aerobic glycolysis because cancer cells prefer glycolysis over OXPHOS to provide sufficient biomass and energy for rapid proliferation." (PMID 39095708, 2024).
cancer (continued). "Further research is necessary to fully elucidate the intricate interplay between METTL3, Pin1, and BRD4 in the context of various cancers." (PMID 39335515, 2024). "Functional experiments have revealed that METTL3 upregulates INC00958, which then interacts with miR‐3619‐5p to elevate the levels of HDGF, thereby promoting lipogenesis and cancer progression in HCC." (PMID 38721006, 2024). "In cancer cells, circ0008399 interacts with WTAP to recruit WTAP/METTL3/METTL14 complex in increasing TNFAIP3 mRNA stability in an m6A-dependent manner." (PMID 38075202, 2024). "Hence, we speculate that METTL3 may be a player in cancer cells’ cellular stemness-related process." (PMID 38966069, 2024). "In BC, METTL3 increases adenylate kinase 4 (AK4) expression to elevate ROS and p38 activity and augment tamoxifen resistance in cancer cells." (PMID 38721006, 2024). "Clinically, up-regulated IGF2BP3, METTL3, and CDC25A show a strong positive correlation in TCGA pan-cancer, including AEG." (PMID 39247830, 2024). "METTL3 has been shown to interact directly with BRD4, a vital transcriptional regulator that plays an essential role in gene expression in cancer cells." (PMID 39335515, 2024). "CESC, BRCA, LUAD, and COAD cell lines express lower amounts of METTL3 and FTO transcripts compared to their healthy counterparts, while WTAP and ALKBH5 expressions differ by cancer type." (PMID 38665783, 2024). "IHC results showed that METTL3, IGF2BP3, and CDC25A expression significantly increased in cancer tissues compared to normal adjacent tissues." (PMID 39247830, 2024). "RNA-seq results revealed that knockdown of METTL3 induced significant alterations in multiple crucial biological processes and downstream pathways, particularly the PI3K/AKT signaling pathway and cancer-related pathways." (PMID 39497721, 2024). "Among m6A regulators, METTL3/14, FTO, ALKBH5, and members of the YTHDF family have been extensively studied for their contributions to RNA regulation and cancer progression." (PMID 39247830, 2024). "METTL3 and IGF2BP3 promote VEGF expression in various cancers, potentially contributing to the immunosuppressive TME." (PMID 39098905, 2024). "It is noteworthy that the dysregulation of METTL3 and METTL14, and consequently m6A methylation, can have a significant impact on cancer progression." (PMID 38148841, 2023). "In cancer, histone methylation upregulates the expression of METTL3, which mediates m6A, and YTHDF2, which recognizes m6A, thereby promoting cancer progression." (PMID 36774341, 2023). "The representative m6A methyltransferases and demethylases, such as ALKBH5, METTL3, and METTL14, have been widely studied in cancer development." (PMID 37647025, 2023). "The expression cor-relationships between METTL3 and its targets, including JAK1, VEGFA, CCND1, and STAT3, was positive in almost all analyzed cancer types." (PMID 38001065, 2023). "Mechanistically, METTL3 serves as the m6A transferase of EGR1 mRNA, leading to its stabilization and activation of the EGR1/Snail regulatory loop, resulting in cancer cell metastasis." (PMID 37015927, 2023). "The inhibition of METTL3 synergized with anti-PD1 immunotherapy, highlighting its potential for improving cancer treatment." (PMID 38072988, 2023). "The METTL3-METTL14 complex is extensively involved in various diseases, such as cancers, cardiovascular disorders, neurological disorders and musculoskeletal diseases." (PMID 37202385, 2023). "METTL3 is the only catalytic subunit of the complex and has been recently reported to regulate EMT in the progression and invasion of human cancers through triggering translation of SNAIL mRNA." (PMID 36945110, 2023). "METTL3 limited the stability and abundance of ANGPTL3 and enhanced several key biological behaviors (proliferation, migration and invasion) of cancer cells." (PMID 37344779, 2023).
cancer (continued). "Recent studies have shown that METTL3/14 can regulate immune cell infiltration in the TIME, highlighting its importance in cancer immunology." (PMID 38187373, 2023). "m6A methylation can influence cancer cell metastasis by increasing epithelial-mesenchymal transition (EMT); conversely, knockdown of METTL3 significantly reduced the expression of Snail, a key transcription factor modulating EMT in cancer metastasis." (PMID 37020540, 2023). "Here, we have found the expression of CCND1 was obviously decreased in METTL3-deleted cells, and the same result was also demonstrated in YTHDF1-silenced cancer cells." (PMID 38001065, 2023). "Other molecules, such as FOXA1, SETD2, Hes5, C/EBP-δ, PRMT5, METTL3, Piwil1, PLK1, ERK1/2, and a series of miRNA, indirectly modulate the sensitivity of cancer cells to drugs by regulating FBXW7." (PMID 36998461, 2023). "It is well known that METTL3-mediated m6A affects targeted mRNA or miRNA, involved in EMT and metastasis of cancer." (PMID 36710350, 2023). "To assess the expression level of METTL3 in various human cancers, we utilized the TIMER2 database for analysis across multiple TCGA cancer and normal tissues." (PMID 38012755, 2023). "Meanwhile, activation of ERK phosphorylates METTL3 and stabilizes its expression by increasing USP5-mediated deubiquitylation, resulting in ERK-activated cancer cell tumorigenesis." (PMID 37015927, 2023). "In terms of direct regulation, METTL3 expression was directly interacted with LncRNA ARHGAP5-AS1, LINC00470 and LncRNA SNHG4 in different cancer cells." (PMID 37365581, 2023). "A previous study reported that METTL3-mediated m6A modification of ankyrin repeat and LEM domain containing 1 (ANKLE1) acted as a cancer regulator mediated CRC cell growth and maintained genomic stability." (PMID 37370759, 2023). "Like METTL3, METTL14 can also affect miRNA maturation in an m6A-dependent manner to promote or suppress cancer progression." (PMID 37437245, 2023). "We find that METTL3a is required for the METTL3–WTAP interaction, RNA m6A deposition, as well as cancer cell proliferation." (PMID 37589705, 2023). "Specifically, METTL3 was able to down-regulate collagentype III α-1 chain (COL3A1), a key factor contributing to themigration, invasion, and adhesion of cancer cells." (PMID 36692498, 2023). "Analyses of m6A regulators and TSs showed that TSs were positively correlated with METTL3, while inversely with METTL14 in most cancer types, although both were m6A methyltransferases adding methyl groups to mRNA." (PMID 36239411, 2023). "Some small activators as well as inhibitors of METTL3, FTO, and YTHDF1–3 were designed to treat different cancers both in vitro and in mouse models." (PMID 36795489, 2023). "With regard to cancer, an m6A score based on the expression of IGF2BP2, IGF2BP3, KIAA1429, METTL3, EIF3H, and LRPPRC was reported as an indicator of pancreatic tumor microenvironment status and was a potential biomarker for patients’ prognosis." (PMID 37903783, 2023). "Besides, several small molecular inhibitors against METTL3 are regarded as promising strategies for cancer persistence and recurrence, and the pharmacological combination of METTL3 inhibitors and chemotherapeutic agents may provide basic principles for future research." (PMID 37915103, 2023). "The involvements of METTL3, METTL14, FTO, and ALKBH5 in many cancers have been investigated, and they demonstrate various roles in different cancers." (PMID 35596159, 2022). "Writers such as METTL3 and METTL14 show cancer-promoting or cancer-suppressive effects on the same or different cancer types." (PMID 35449086, 2022). "Lower m6A levels in myeloid cells enhance cancer progression by blocking the YTHDF1-mediated translation of SPRED2, and knockout of METTL3 induced a higher count of M2 macrophages in the TME69." (PMID 35794212, 2022).
cancer (continued). "Recent studies indicated that m6A modifications of mRNAs are increased in cancer cells during EMT, and that deletion of the m6A writer, METTL3, can impair EMT, while deletion of the m6A eraser, FTO, can promote EMT." (PMID 35279145, 2022). "Another study revealed that the epithelial-mesenchymal transition (EMT) was regulated by METTL3 in HCC cells through the methylating of CDS of Snail and then triggering polysome-mediated translation of Snail mRNA in cancer cells." (PMID 35280730, 2022). "Additionally, the knockdown of METTL3 was shown to significantly inhibit the expression of translation initiation factors, including eIF (2B3, 3b, 3c, 3d, 4A1, and 5/5A), thereby inhibiting lung adenocarcinoma proliferation and reducing the invasive ability of cancer cells." (PMID 36360287, 2022). "The regulatory network of “writer” METTL3, “reader” YTHDF1, and “target” FRAS1 inspires the understanding of m6A-dependent gene regulatory mechanism in cancer biology, which offers a possibility of m6A regulators as promising biomarkers in NSCLC." (PMID 36008805, 2022). "Remarkably, when comparing BlCa with NUT, we found that not only METTL14 but also METTL3, VIRMA, and ALKBH5 expression was significantly decreased in cancer tissues." (PMID 35048498, 2022). "The inhibitors and regulators of m6A modification regulators have been explored as therapeutic approaches for treating cancer, such as FTO inhibitors (including rhein, R-2HG, IOX3, and FB23) and METTL3/METTL14 inhibitors (3-deazaadenosine)." (PMID 35154270, 2022). "METTL3 was found to upregulate glycolysis in CRC by stabilizing HK2 and SLC2A1 in an m6A-IGF2BP2/3-dependent manner, leading to cancer progression." (PMID 35804965, 2022). "METTL3 binds to EGFR mRNA near the stop codon and is responsible for its m6A modification, modulating EGFR mRNA stability in human cancer cells." (PMID 35001873, 2022). "In bladder cancer, METTL3 reduces the expression of PTEN via expediting the maturity of pri-miR221/222, resulting in the malignant proliferation of cancer cells." (PMID 35804965, 2022). "In breast cancer, tamoxifen-resistant cancer cells highly express adenylate kinase 4 (AK4) and METTL3." (PMID 35022030, 2022). "Meanwhile, METTL3 can directly activate PI3K-Akt-mTOR signaling pathway and promote the proliferation, migration and invasion of cancer cells in retinoblastoma." (PMID 35022030, 2022). "In order to confirm that METTL3 and LINC00662 were related to the angiogenesis of CRC, 64 pairs of CRC and para-cancer tissues were collected in this study." (PMID 36114893, 2022). "Several members (e.g. METTL3, FTO and IGF2BPs) actively participate in diverse human cancers such as acute lymphoblastic leukemia, breast cancer and endometrial cancer." (PMID 35524319, 2022). "Notwithstanding the limitations of this study (e.g., its retrospective nature and subjectivity of IHC scoring), METTL3/METTL14 methyltransferase complex downregulation seems to dictate reduced m6A levels and contribute to cancer progression." (PMID 35048498, 2022). "Therefore, METTL3 may become a new potential therapeutic target for cancer." (PMID 36114893, 2022). "These different effects may be attributed to the fact that METTL3 mainly acts on different genes in different cancers, and the addition of m6A modification to different genes ultimately leads to different biological effects, thus showing conflicting effects in different cancers." (PMID 36360248, 2022). "The results show that knockout METTL3 and METTL14 down-regulates the expression of SRF in cells, while in the SRF-3’-UTR mutant cancer cells, the deletion of METTL3 and METTL14 don’t affect the expression of SRF." (PMID 35022030, 2022). "To investigate the contribution of METTL3 acetylation in controlling cancer metastasis in vivo, we generated LM2 METTL3 reconstituting cells (LM2, a derivative of MDA-MB-231 cells with strong lung metastatic potential)." (PMID 36289222, 2022).
cancer (continued). "These methyltransferases all play an important role in forming METTL3-METTL14 complexes in different links, affecting cancer cell proliferation and migration." (PMID 35707365, 2022). "During pancreatic cancer progression, NKAP leads to the overmaturation of miR-25 under overexpressed METTL3 m6A modification, thereby inhibiting PHLPP2 and activating the AKT-p70S6K signaling to promote cancer progression." (PMID 36561529, 2022). "M6A methyltransferase [such as METTL3, METTL14, and METTL16] participates in the progression of malignant tumors by read, write, or erase m6A on bound RNA24." (PMID 33741902, 2021). "Several members (e.g., METTL3, METTL14, FTO, ALKBH5, and YTHDF2) actively participate in human cancers such as acute myeloid leukemia, glioblastoma, breast cancer, and endometrial cancer." (PMID 34363020, 2021). "Our data indicate ADAR1 as one of the main targets of METTL3 controlling cell proliferation and connecting, in a new molecular pathway, two key proteins (METTL3 and CDK2) important for cancer progression." (PMID 33509238, 2021). "METTL3, as a critical subunit of the METTL3-METTL14 methyltransferase complex, has been validated to contribute to the process of cancer." (PMID 34046411, 2021). "Similar to our findings, METTL3-induced m6A modification was involved in the upregulation of CBX8, which contributed to increased cancer stemness and decreased chemosensitivity in CC." (PMID 34544413, 2021). "For example, in NSCLC, METTL3 regulated the Dicer cleavage of pre-miR-143-3p through the miR-143-3p/VASH1 axis and played an essential role in cancer metastasis." (PMID 34345203, 2021). "As critical components of the m6A system, both METTL3 and WTAP have been shown to play an important role in various types of cancers." (PMID 34809621, 2021). "METTL3 is a methyltransferase to primarily enhance m6A modification to facilitate the development of EMT, invasion, and metastasis in various types of cancers." (PMID 34666602, 2021). "Developing inhibitors of oncogenic m6A regulator like METTL3 and agonist of antitumor m6A regulator like METTL14 is a promising therapeutic strategy to overcome cancer, improve immune responses and reduce drug resistance." (PMID 33456561, 2021). "Surprisingly, even though METTL3 and METTL14 show different expression levels and functions in urological cancers, they both participate in cancer progression through cell growth- and cell death-related pathways." (PMID 35004679, 2021). "METTL3, TYTHDF1, YTHFDF2 and HNRNPC were highly expressed in cancer tissues and low in normal control tissues." (PMID 34521394, 2021). "METTL3-mediated m6A modification and upregulation of miR-1246 thus negatively regulate SPRED2 and inactivate MAPK pathway to promote cancer metastasis." (PMID 33814008, 2021). "The existing reports of methyltransferases are primarily focusing on methyltransferase-like 3 (METTL3), methyltransferase-like 14 (METTL14) and KIAA1429, which play a dominant role in the regulation between m6A methylation and cancer metastasis." (PMID 34211849, 2021). "In their opinion, the up-regulated METTL3 leads to the increased m6A methylation of SETD7 and KLF4, two cancer suppressors." (PMID 32612834, 2020). "Studies have shown that METTL3 upregulates the m6A levels of HK2 and GLUT1, depletion of which inhibits cancer cell proliferation and colony formation." (PMID 32709063, 2020). "The elevated expression of METTL3 in LUAD is thought to promote growth and invasion of cancer cells." (PMID 32258108, 2020). "In HCC, METTL3-mediated m6A leads to upregulation of LINC00958 by enhancing its stability, thereby promoting cancer progression." (PMID 32911345, 2020). "As a writer, METTL3 targets oncogenes like EGFR, TAZ, MK2 and DNMT3, and enhances the expression of them to nourish the cancer cells with better survival, growth and invasion." (PMID 32612834, 2020).